HSPA1B (heat shock protein family A (Hsp70) member 1B)
Diseases named in the same sentence as HSPA1B in open-access papers (continued):
Sharing a sentence is not in itself a finding about the gene and the disease.
tumor (continued). "The C2 cluster (heat shock proteins and molecular chaperones) showed high expression of HSPA1B and DNAJB1, suggesting that tumor cells experience high biological stress and rely on these proteins to maintain protein folding homeostasis." (PMID 40463392, 2025). "Since HSPA1B is negatively regulated by both UBASH3A and UBASH3B, its tumor suppressor activity is dependent upon balance between the level of these UBASH3 proteins, negatively and positively regulated by FLI1, respectively." (PMID 38461240, 2024). "Generally, heat shock protein family genes (HSPD1, HSPA1B, HSP90AB1, and HSPH1) enhance tumor growth and invasion through complex intracellular signaling networks." (PMID 37533434, 2023). "In contrast, tumor T cells’ DEGs coded for heat shock proteins, such as HSPA6, HSPA1A, and HSPA1B in addition to genes related to T cell development and function, such as NR4A1 and NR4A2." (PMID 35534852, 2022). "The higher HSPA1A, HSPA1B, and HSPA13 expressions were positively correlated with higher cancer stage and tumor grade." (PMID 34059060, 2021). "Upregulated within the tumor-infiltrating CD4+ T cells were heat shock proteins (HSPA1A and HSPA1B), Jun and FOS constituents (FOS, JUN, and JUNB), MHC-II molecules (HLA-DRB), and secreted molecules (CCL5, GZMA, and GZMK)." (PMID 33504936, 2021). "As the most prominent tissue‐resident ILC3 subsets in tumour, ILC3‐HSPA1B is distinguished by upregulated expression of cell stress‐related genes (e.g., HSPA1B, HSPA1A, and JUN), all of which have been reported to be involved in cellular stress responses and adaptive mechanisms." (PMID 41527493, 2026). "Additionally, genes involved in the cellular response to stress were commonly upregulated in tumor C1 and C2 NK cells (HSP90AA1, HSPA1B, HSPH1, DNAJB1, PSMB9, CSTP1)." (PMID 41082397, 2026). "We also observed a downregulation of stress response proteins (HSPA1A/HSPA1B, HSPA5, SERPINH1), suggesting that TSA might affect cellular stress response pathways, potentially impacting tumor cell survival." (PMID 40429900, 2025). "HSPA1B is rarely reported in AML, but it has been shown to correlate with the progression of microvascular complications, suggesting its importance in tumorigenesis and tumor immunity." (PMID 39213256, 2024). "Additionally, the heat shock protein family genes (HSPD1, HSPA1B, and HSP90AB1) facilitate tumor growth and invasion via intricate intracellular signaling networks." (PMID 37533434, 2023). "Among non-tumor cells, high NDUFA4L2 expression in fibroblasts may promote tumor progression, whereas high HSPA1B expression in Tcms may exert antitumor effects." (PMID 37333982, 2023). "The HSPA1B+ Tcm subpopulation was significantly increased in the HCC group, and HSPA1B was significantly enriched in all cell types in the HCC group, suggesting its involvement in remodeling of the tumor ecological niche in HCC." (PMID 37333982, 2023). "Among non-tumor cells, high NDUFA4L2 expression in fibroblasts may promote tumor progression, while high HSPA1B expression in central memory T cells may exert anti-tumor effects." (PMID 37333982, 2023). "Moreover, EC (HSPA1B) in the TNBC tissues exhibited altered fluid shear stress compared to the normal human breast tissues, which participates in tumor metastasis." (PMID 35265720, 2022). "In conclusion, HSPA1B+ Tcm subpopulation plays an important role in the immune response to HCC, suggesting that increasing the abundance of this subpopulation may help inhibit tumor growth and metastasis." (PMID 37333982, 2023).
cancer (24 papers, 2013 to 2026). A tumor composed of atypical neoplastic, often pleomorphic cells that invade other tissues. "We also investigated that increased some heat shock proteins (HSPs), HSPA1A and HSPA1B were upregulated in advanced cancer." (PMID 38719807, 2024). "The HSP70s family includes constitutively expressed members HSC70 (HSPA8) and stress-inducible member HSP70 (HSPA1A/HSPA1B), which have been demonstrated to control protein maturation and proper folding in cancer cells." (PMID 36773708, 2023). "When validated by PCR, important cancer-related genes such as NOXA (apoptotic gene), GADD34 (cell cycle regulator) and HSPA1A, HSPA1B (encoding HSP70 proteins) were up-regulated by at least two folds upon PRIMA-1 treatment." (PMID 27533450, 2016). "Intriguingly, a recent meta-analysis study indicated that individuals with HSPA1B AG/GG genotype, which seem to protect from IPF, have an increased risk of cancer." (PMID 26496868, 2015). "Three different siRNAs or siRNA pools each for HSPA1A/HSPA1B and HSPA8 and, in addition, siRNA pools against HSPA2, which is expressed in a tissue specific manner and was implicated in cancer cell survival, and HSPA5 were utilized." (PMID 24265689, 2013). "Whether the down-regulation of Hspa1b, P4ha1, and Banp genes in whole blood and in the hippocampus in the present study is involved in the body’s self-protective mechanism in preventing low dose rate irradiation-induced early-life stress and cancers remains unknown." (PMID 39272995, 2024). "A single-cell pan-cancer study last year detected a novel CD4+/CD8+ T-cell subtype characterized by a high expression of heat shock protein genes such as HSPA1A, HSPA1B, and other stress-response-related genes, known as the stress response (TSTR)." (PMID 38629070, 2024). "Importantly, among three miRNAs, only miR-570 showed partial complemental with 3′-UTR sequences in not only human HSPA1A and BAG3 but also HSPA1B and HSP90AA1 (highlighted in red), which are involved in cancer progression." (PMID 36114410, 2022). "In addition, the four overlapping target genes of miR-7977 (CCL22, STK4, HSPA1B, and ACTR2) in all three databases were reported to have a key role in cancer formation and metastasis." (PMID 32328453, 2020). "Depletion of Hsp70 using antisense RNA against HSPA1A/HSPA1B mRNAs induced apoptosis in several cancer cell lines but not in non-malignant cells." (PMID 24265689, 2013). "In this study we demonstrate that down-regulation of the heat-inducible Hsp70 (HSPA1A/HSPA1B) to less than 10% of its cellular level does not suffice to challenge the different cancer cells tested." (PMID 24265689, 2013). "Since down-regulation of both major cytoplasmic Hsp70s, Hsp70 (HSPA1A, HSPA1B) and Hsc70 (HAPA8), was necessary to reduce viability of cancer cells from different lines, paralog specificity does not appear to be a desideratum for a clinically usable Hsp70 inhibitor." (PMID 24265689, 2013).
infection (18 papers, 2008 to 2025). The state of being infected such as from the introduction of a foreign agent such as serum, vaccine, antigenic substance or organism. "In contrast, Hspa1a and Hspa1b were inhibited throughout infection but increased suddenly at 48 hpi." (PMID 36830716, 2023). "Two proteins were inversely regulated after infection with the attenuated E75CV1 strain: HSPA1B and vimentin." (PMID 30208957, 2018). "In addition, dnajb1b and hspa1a show a more consistent expression trend compared to hspa1b, as their expression levels both increase with infection time." (PMID 39063205, 2024). "Notably, in the mock transcriptomic data, there are higher levels of sequenced HSPA1A and HSPA1B transcripts in A549 cells compared to MRC-5 cells prior to infection with ChAdOx1 nCoV-19 with the reverse being true for PML transcripts." (PMID 33722288, 2021). "Of note, Hspa1b was found to be upregulated in both mouse strains during infection." (PMID 29430463, 2017). "Interestingly, in cluster 3 of DEGs between normal + infection group and undernutrition 75% + infection group, hub genes Dnaja1 (0.49-fold change), Hspa1a (0.12-fold change), Hspa1b (0.20-fold change) and Hsph1 (0.35-fold change) were also downregulated in undernutrition 75% + infection group." (PMID 38185681, 2024). "Post-infection, members of the heat shock protein 70 (HSP70) family, specifically HSPA1B, and transcription factors ATF4, DDIT3, and JUNB showed increased expression (p < 0.05)." (PMID 39600797, 2024). "In this study, HSPA5, HSPA1B, HSP90B1 and HSPA6 were up-regulated at 24 hpi to various degrees following CPIV3 -infection of MDBK cells." (PMID 31101113, 2019). "Different expression levels of HSPA1B were detected by western blot analysis at 24 hpi and 48 hpi after CPIV3 -infection of MDBK cells." (PMID 31101113, 2019). "Genes in group E were slightly up-regulated as early as 8 hpi during infection; some heat shock proteins, such as HSPB1, HSPA6, HSPA1B were found in this group." (PMID 18811943, 2008).
infectious disease (1 paper, 2024). A disorder directly resulting from the presence and activity of a microbial, viral, or parasitic agent in humans. "Overrepresentation analyses of upregulated proteins yielded six Reactome pathways enriched, highlighting “HSA-5663205: Infectious disease” (strength = 1.19; FDR = 0.003), which included the proteins RPL18A, PSMA5, HSPA1B, RPL35A, and ISG15." (PMID 39409176, 2024).
HSPA1B also shares sentences with these, for which no sentence is quoted: neurodegenerative disease (4 papers); brain ischemia (2); gastric cancer (2); measles (2); anemia (1); atherosclerosis (1); Azoospermia (1); bacterial infections (1); basal cell carcinoma (1); behavioral disorders (1); bipolar disorder (1); cataract (1); cerebral infarction (1); Cerebral ischemia (1); chronic heart failure (1); cocaine use disorder (1); colorectal polyp (1); coronary artery disease (1); depression (1); diffuse gastric cancer (1); Epstein-Barr virus infection (1); experimental autoimmune encephalomyelitis (1); falciparum malaria (1); fibrosarcoma (1); hyperlipidemia (1); Hypoglycemia (1); infarction (1); inflammation (1); lung adenocarcinoma (1); Lung Disease (1).
A further 11 diseases each share a sentence with HSPA1B in 1 paper.